NRP1 (neuropilin 1)
Diseases named in the same sentence as NRP1 in open-access papers (continued):
Sharing a sentence is not in itself a finding about the gene and the disease.
cancer (continued). "The presence of VEGR2/NRP1 trans‐complexes in PDAC, but not in GAC tumors, was associated with decreased vessel formation, reduced cancer cell proliferation, and improved patient survival." (PMID 30027561, 2018). "For example, although bevacizumab has shown promising anti-angiogenic activity, it does not inhibit the interaction between VEGF RTKs and neuropilin-1 (NRPs), which are contributing factors to cancer stem cell survival." (PMID 28410237, 2017). "As a result, NRP1 might interact with other TGF-β receptors, resulting in TGF-β binding and activation, thereby facilitating cancer metastasis." (PMID 27014911, 2016). "Together, the data support a negative association between important cancer targets that possess opposing functions, LKB1 on one hand, and NRP-1/NEDD9 on the other." (PMID 26701889, 2016). "Subsequently, several studies highlighted that NRP-1 was aberrantly expressed in several cancer types, including PDAC, and was involved in a plethora of cancer initiating and promoting pathways due to its distinctive ability to bind numerous growth factors and ligands." (PMID 27542226, 2016). "In this study, we gained insight into the positive and negative mediators of pro-metastatic NRP-1 functions in multiple cancers." (PMID 26701889, 2016). "BRCA1 basal cancers, when compared to sporadic basal cancers showed reduced positivity for FOXP1 (6/20 [30 %] vs. 37/49 [76 %], p < 0.001), cyclin D1 (8/22 [36 %] vs. 30/46 [65 %], p = 0.025), NRP1 (2/20 [10 %] vs. 23/46 [50 %], p = 0.002) and CD99 (17/20 [85 %] vs. 7/19 [37 %], p = 0.002)." (PMID 26152113, 2015). "In the present study, we showed that the VEGF-A/NRP1 signaling pathway promoted cancer cell proliferation even though cancer cells do not express VEGFR1 or VEGFR2." (PMID 26209534, 2015). "Since Nrp1 can act as a co-receptor for TGF-β in cancer cells, it would be interesting to determine whether the TGF-β–mediated miR-181a/b regulation we observe in the retina also involves Nrp-1 regulation." (PMID 26641497, 2015). "Of the six proteins that were investigated via immunohistochemistry, four (cyclin D1, FOXP1, NRP1 and CD99) showed reduced expression in BRCA1 cancers in the initial cohort with reduced expression for FOXP1, cyclin D1 and NRP1 subsequently confirmed in the validation cohort." (PMID 26152113, 2015). "The expression of Cyclin D1, FOXP1, FIH-1, pan-ERβ, NRP1 and CD99, predicted to be regulated by BRCA1 specific miRNAs by computer prediction algorithms, was assessed via immunohistochemistry in a cohort of 35 BRCA1 and 52 sporadic basal-like cancers." (PMID 26152113, 2015). "Collectively, these results support that expression of Nrp1 on CD8+ T cells does not play a role in the tolerant phenotype that normally limits responses during adoptive T cell immunotherapy for cancer in mice." (PMID 25343644, 2014). "Therefore, much remains to be studied regarding the exact role of NRP1 and the relationship between the SEMA3s and VEGF in different types of cancer." (PMID 22926477, 2012). "In the present study, we investigated the effects of EG3287 on the functions of human carcinoma lung A549, kidney ACHN, and prostate DU145 cells expressing NRP1 but lacking VEGFR-2, and the mechanisms underlying these effects." (PMID 20087344, 2010). "Despite the evidence concerning the role of NRP1 in cancer progression and poor prognosis, it has not been reported whether extracellular stiffness correlates with NRP1 expression in cancer cells." (PMID 38903533, 2024). "In addition to the discovery of NRP1 as a SARS-CoV-2 entry coreceptor along with ACE2, we have assembled the pathological roles of NRPs and their involvement in clinical diseases, particularly highlighting the participation of NRPs in cancer." (PMID 35955539, 2022). "Notably, the authors observed increased expression of αvβ3 and NRP-1 in cancer tissues compared with noncancerous tissues, thus indicating the cancer targeting potential for iRGD-EXO." (PMID 36297407, 2022).
cancer (continued). "Indeed, NRP1 and NRP2 expression has been observed in cancer cells demonstrating a functional role." (PMID 33121034, 2020). "In the other cancer types, upregulation of NRP1 was modest or not observed." (PMID 31880322, 2020). "There is evidence that NRP-1, despite the lack of catalytic activity, also serves as an independent mediator of blood vessel development in cancerous tumors and that its expression on the surface of cancerous cells is increased and often associated with poor prognosis." (PMID 32183142, 2020). "However, a deeper understanding is needed to elucidate the effect of NRP1 and NRP2 on cancer cells." (PMID 30871059, 2019). "With the aim of designing a functionalized nanoscaffold to target cancer, the coat protein (CP) of Tobacco mosaic virus (TMV) was tested as nanocarrier for an insoluble, highly hydrophobic peptide that targets the transmembrane domain of the Neuropilin-1 (NRP1) receptor in cancer cells." (PMID 31652529, 2019). "We propose that the VEGFR2/NRP1 complex status could be of significant value as a prognostic marker and a potential predictive marker of anti‐angiogenic therapy in PDAC and possibly other cancer types." (PMID 30027561, 2018). "However, our previous work utilizing genetic mouse models that allowed probing for NRP1's function specifically in complex formation with VEGFR2 13 forms the basis for the current work, where we have translated findings from mouse to human cancer." (PMID 30027561, 2018). "Compared with sporadic basal cancers, BRCA1 cancers showed reduced positivity for proteins predicted to be regulated by miRNAs: FOXP1 (6/20[30 %] vs. 37/49[76 %], p < 0.001), cyclin D1 (8/22[36 %] vs. 30/46[65 %], p = 0.025), NRP1 (2/20[10 %] vs. 23/46[50 %], p = 0.002)." (PMID 26152113, 2015). "To definitively assess whether Nrp1 expression impacts CD8+ T cell function over time, we directly compared WT and nrp1f/f T cells for efficacy in our model of adoptive T cell immunotherapy for cancer." (PMID 25343644, 2014). "Despite a lack of involvement in the tolerant phenotype, Nrp1 may represent a valuable biomarker for such T cells in cancer patients." (PMID 25343644, 2014). "Although Nrp1+ CD4+ T cells may co-express CD25 and exert regulatory function in some cancer-draining lymph nodes, in non-malignant lymph nodes and tonsils, Nrp1+ CD4+ T cells have a non-regulatory (CD25- FoxP3-) memory (CD45RA- CD45RO+) phenotype." (PMID 24386482, 2013). "Since Nrp1 and Nrp2 have similar but not completely overlapping roles in angiogenesis and cancer, it might be desirable to therapeutically block both." (PMID 22948112, 2012). "However, the cell–matrix adhesive properties of NRP1 have not been investigated previously in carcinoma cells expressing endogenous NRP1." (PMID 20087344, 2010). "Investigating whether stiffness-induced NRP1 expression involves mechanotransducer pathways, including proteins like YAP and the activation of the Rho and ROCK signaling pathways, which also facilitate NRP1 ligand activation and thus promote cancer cell malignancy, could provide valuable insights." (PMID 38903533, 2024). "In addition, conforming with our bioinformatics analysis, previous research found that NRP1 might modulate EMT to not only contribute to the growth and metastasis of tumors, but also induce drug-resistance and radiation resistance in cancers." (PMID 35571014, 2022). "However, in our previous study, we reported that this NRP1-driven drug resistance was not dependent on VEGF-A, which is a major autocrine NRP-1 ligand implicated in sustaining viability and self-renewal of cancer cells." (PMID 32784465, 2020). "Furthermore, Neuropilin-1 (NRP-1) and Neuropilin-2 (NRP-2) transmembrane proteoglycans, as well as hyaluronic acid (HA) fragments resulting from the hydrolysis of carbohydrate chains in proteoglycans by HYAL hyaluronidase, also display pro-angiogenic properties in several cancer models." (PMID 31157165, 2019).
cancer (continued). "Anti-EGFR therapy in the context of cancer treatment may have cardiotoxic side effects, maybe due to EC dysfunction, because EGFR, which is normally involved in EGF/neuregulin signaling, can also form a holoreceptor with NRP1 and elicits a repellent SEMA3D signal in venous ECs." (PMID 30717262, 2019). "Thus, although anti-Nrp1 therapy may not be markedly toxic on its own, it may produce important adverse effects when combined with some anti-cancer agents." (PMID 22948112, 2012). "Of all cancer forms analyzed, CCRCC and PRCC displayed the highest expression levels for ACE2 and NRP1 mRNA, whereas again TMPRSS2 expression was lower but not negligible." (PMID 36595529, 2023). "Neuropilin-1 (NRP-1) is a non-tyrosine kinase receptor interacting with multiple signaling pathways that underpin the biological behavior and fate of cancer cells." (PMID 31572065, 2019). "Down regulation of NRP1 in KRASmt cells decreased the phosphorylation of SMAD2, but there was no change in SMAD2 phosphorylation in KRASwt cancer cells upon NRP1 knockdown." (PMID 29018205, 2017). "Expression of the VEGFR1 and VEGFR3 receptors and NRP1 and NRP2 (data not shown) was not modified in JSRV-induced cancers when compared to normal lungs." (PMID 29137669, 2017). "Mechanistically, miR-148a appears to suppress the extravasation process of cancer cells, likely by targeting two genes WNT1 and NRP1 in a cell non-autonomous manner." (PMID 26967387, 2016). "In this section we will consider two of these proteins, both of which are directly related to cancer: EGFR, which is also identified by iPAC, and NRP1, which is not identified by iPAC." (PMID 24669769, 2014). "Concerning non-malignant cells, anti-apoptotic effects of NRP1 in response to binding of VEGF have been reported for cell types like mesenchymal stem cells, neurons or cancer cells." (PMID 23251405, 2012). "Notably, metabolic stressors present in the TME including hypoxia and nutrient deprivation results in the lysosomal degradation of NRP1, but not NRP2 on endothelial cells and carcinoma cells via autophagy." (PMID 35651620, 2022). "In addition, NRP1, CD276, and VSIR showed obvious positive correlation with SLC7A11 expression in most cancers, although the drugs targeted at these checkpoints have not been applied in clinic." (PMID 34938318, 2021). "Neuropilin-1 (NRP-1) is a non-tyrosine kinase transmembrane molecule overexpressed in gastrointestinal cancers, and serves as a co-receptor for several cellular signaling pathways involved in cancer progression." (PMID 32801339, 2020). "While we did not identify a role for Nrp1 in the regulation of CD8+ T cell function or survival in a tolerant environment, our results should not be interpreted to imply a lack of utility for Nrp1 blockade in cancer therapy." (PMID 25343644, 2014). "TMPRSS2 and AXL was down-regulated often in cancers but SCARB1 showed the reverse trends, while all of three was shown to be expressed abnormally more frequently than ACE2 and NRP1, which could not provide an expression patten possibly due to their limited situations." (PMID 36875081, 2023). "Therefore, it can be speculated that besides direct inhibitory effects of Sema3A-Nrp1 interaction on PDGF-induced HASMC proliferation, Nrp1 might compete with PDGFR to bind its ligand which, unlike cancer studies, further weakened the cellular function." (PMID 27791986, 2016).
infection (154 papers, 2008 to 2026). The state of being infected such as from the introduction of a foreign agent such as serum, vaccine, antigenic substance or organism. "In this study, we focus on the identification of peptide inhibitors that dual target RBD and NRP1, with the aim of providing a novel therapeutic strategy to address infections caused by mutant strains." (PMID 41383479, 2025). "In our proposed model, drugs with prior FDA approval will be repurposed for transient reduction of NRP1 expression in macrophages to reduce the risk of infection with SARS-CoV2." (PMID 39512370, 2024). "In in vitro infection assays, Nrp1 inhibited infection, an effect that was associated with its incorporation into cell-free virions produced by HTLV-1-infected T-cell lines." (PMID 37375521, 2023). "We analyzed the CendR motif of spike protein and performed in silico molecular docking with neuropilin-1 (Nrp1), a receptor–ligand interaction known to support infection by the original variant." (PMID 35447881, 2022). "Using the Vero E6 model we showed that prolonged hypoxia reduces the expression levels of cell surface ACE2 and NRP1, resulting in a reduced susceptibility to infection by pseudotyped viral particles expressing the spike of SARS-CoV-2." (PMID 34013835, 2021). "NRP1 expression alone caused lower levels of infection, which were detectable only with increasing virus titer." (PMID 33082293, 2020). "The higher proportion of NRP1+ olfactory neurons in the young population may be associated with the increased neuronal infection." (PMID 38483537, 2024). "Similarly, NRP1 has been implicated in the infection of macrophage reservoirs in the nasal epithelium as well as astrocytes in the brain." (PMID 39512370, 2024). "SARS-CoV-2 uses the spike protein for cell entry, and its cleavage facilitates attachment to NRP1; therefore, tissues with increased membrane NRP1 have increased infectivity risk and increased circulating NRP1 expression may raise infection risk." (PMID 34248841, 2021). "When deleted before infection, Nrp1 deficiency inhibited the secondary response." (PMID 31118303, 2019). "However, by PbA infection of Treg-specific Nrp-1 deficient mice (Nrp-1fl/fl x Foxp3cretg) we could exclude an effect of Treg-derived Nrp-1 on the immune cell infiltration in the brain and ECM development." (PMID 38019895, 2023). "Studies have shown that blocking the interaction between NRP1 and the C-terminal fragment of the viral S1 subunit can reduce infection efficiency." (PMID 41383479, 2025). "A hypothetical model depicting the binding of inhibitors to NRP1, validated by their disruption of the NRP1-spike protein interaction, suggests a promising strategy for mitigating infection." (PMID 39908250, 2025). "For example, both EBV and KSHV gB bind NRP1, activating downstream signaling pathways that promote internalization and infection in nasopharyngeal epithelial cells and mesenchymal stem cells, respectively." (PMID 40632757, 2025). "During infection, NRP1-promoted virus entry is thought to facilitate the infection of cells with low levels of ACE2 expression, such as olfactory endothelial cells, possibly aiding the separation of S1 and S2 subunits of the Spike protein." (PMID 39697632, 2024). "Our findings revealed that the levels of Gata2, Fat4 and Pkd1, which are related to cell polarization, as well as Egfl7, Nrp1 and Foxc2, which are related to valve development, were downregulated after infection." (PMID 38638427, 2024). "Utilizing published single-cell RNA sequencing data obtained from simulated SARS-CoV-2 infection in human bronchial epithelial cells (HBECs), we found that ciliated cells with high levels of NRP1 are prominently targeted by the virus during infection." (PMID 38674009, 2024). "With the onset of the first neurological symptoms of ECM on day 5 post PbA infection, we measured a significant increase of Nrp-1 expression in CD8+ T cells in the spleen, blood and brain." (PMID 38019895, 2023).
infection (continued). "A trend toward reduced ErbB2 levels, albeit statistically nonsignificant, was also measured at the early time point after infection, whereas the level of cell surface NRP1 was increased upon infection." (PMID 37581931, 2023). "MuHV-1 binding to neuropilin-1 is important for infection in endothelial, fibroblast and macrophage cell lines." (PMID 38029264, 2023). "HEK293T cells were transfected with the set of single-cycle, replication-dependent luciferase infection assay plasmids and co-transfected with an expression vector for full-length Nrp1 or the deletion mutant." (PMID 37375521, 2023). "Upon PbA infection, we detected a slight decrease of the proportion of Nrp-1-expressing Tregs in the spleen and peripheral blood." (PMID 38019895, 2023). "With less SEMA3C, more NRP1 receptors are available for CoV2 binding, thus increasing the infection of other NRP1-presenting cells, including respiratory and olfactory epithelium." (PMID 38203569, 2023). "With this approach, we observed that Jurkat-HBZ cells co-transfected with the shRNA vector targeting NRP1 produced a higher level of infection than cells co-transfected with the shGFP control vector." (PMID 37375521, 2023). "Knocking out Nrp-1 showed early viral gene expression and reduced infection rates in endothelial cells, fibroblasts, and macrophages." (PMID 37794981, 2023). "This comparison of recently established HTLV-1-immortalized cells and long-term HTLV-1 cell lines suggests that Nrp1 can be activated early in the course of infection." (PMID 37375521, 2023). "In conclusion, this report provides evidence of the presence of ACE-2, TMPRSS-2, and Neuropilin-1 proteins on primary pericytes and astrocytes and has demonstrated infection of SARS-CoV-2 in these cells." (PMID 37239978, 2023). "Blocking Nrp-1 using anti-Nrp-1 antibodies reduced the infection drastically, suggesting the importance of Nrp1 in establishing MCMV infection." (PMID 37794981, 2023). "Overall, we analyzed the impact of T cell-expressed Nrp-1 in two distinct infections models, in which overwhelming CD8+ T cell responses induce immunopathologies in the brain and the liver." (PMID 38019895, 2023). "In this context, we explored NRP1 expression in hACE2 and human primary hepatocytes after infection (, b)." (PMID 35978143, 2022). "In contrast, the presence of NP+ and SARS-CoV-2 mRNA expression levels were comparable between WT and NRP1 KO kidney organoids upon infection." (PMID 35561674, 2022). "Together, maximum infection potentiation was observed when Nrp1 and ACE2 were co-expressed on the same cell types in the same tissues." (PMID 35447881, 2022). "EBV gB is reported to directly interact with the entry factor, neuropilin 1 (NRP1) during the infection process of nasopharyngeal epithelial cells." (PMID 35711430, 2022). "treatment of primary astrocytes with a neutralizing anti-ACE2 antibody did not significantly impair SARS-CoV-2 infection, while treatment with anti-NRP1 antibody strongly and significantly blocked infection." (PMID 36314791, 2022). "We and others recently demonstrated that SARS-CoV-2 directly interacts with NRP1 at the cell surface to enhance cellular infection." (PMID 35696571, 2022). "We next examined the expression of reported receptors for SARS-CoV-2 in multi-tissues post infection and observed that Neuropilin-1 (NRP1) was significantly up-regulated in cerebral cortex." (PMID 35377064, 2022). "NRP1 is a potential candidate entry factor for infection, as it has been demonstrated to be a SARS-CoV-2 host factor." (PMID 35858406, 2022). "We observed NRP1 RNA expression in primary tissue, specifically in cortical neurons—a population, however, where we observed minimal infection." (PMID 35858406, 2022). "While coexpression of NRP1 with ACE2 and TMRPSS2 increased the infection, monoclonal antibody targeting the b1b2 extracellular domain of NRP1 significantly inhibited the infection." (PMID 34803446, 2021).